MMP9 (matrix metallopeptidase 9)
Diseases named in the same sentence as MMP9 in open-access papers (continued):
Sharing a sentence is not in itself a finding about the gene and the disease.
breast carcinoma (continued). "This in turn increased breast cancer cell migration and invasion by activating its downstream effector proteins beta-catenin and MMP9." (PMID 38068928, 2023). "MMP-9 cleaved fibronectin can bind to αvβ6 integrins and foster the migration of breast cancer cells." (PMID 36910158, 2023). "The combination of focal adhesion dynamism and the basement membranes degradation by FAK-dependent MMP-9 gene upregulation leads to increased cell motility and migration generating and maintaining the invasive phenotype of breast cancer." (PMID 37649088, 2023). "This suggests that obesity impacts breast cancer progression by increasing the expression of key marker proteins of metastasis (i.e., MMP-9 and β-catenin) through FAK activation." (PMID 38068928, 2023). "The effects of a C. versicolor aqueous extract were also evaluated in mouse mammary carcinoma 4T1 cells and a 4T1-tumor-bearing mouse model, showing significant inhibition of cell migration, invasion, and MMP9 enzyme activity and protein downregulation." (PMID 37373268, 2023). "Further, BCP-1 demonstrated antimetastatic potential by reducing MMP-9 expression and cell migration in both breast cancer cell lines." (PMID 37175359, 2023). "MMP-9 is highly upregulated in breast cancers, facilitating the infiltration of tumor cells and angiogenesis, mainly through the degradation of the basal membrane." (PMID 37372062, 2023). "For example, an anti-thrombotic agent based on calcium phosphate nanoparticles coated with heparin strongly reduced ICAM-1, VCAM-1, and MMP-9 in pre-metastatic lungs of murine breast cancers." (PMID 37350937, 2023). "In vitro-cultivated human breast cancer cells displayed significant alterations in the matrix metalloproteinase-9 (MMP-9) levels." (PMID 37835481, 2023). "Co-expression analysis using the TCGA database identified a positive relationship between CD44 and MMP-9 in breast cancer." (PMID 37185776, 2023). "The results of the MTT assay on the human breast cancer MCF-7 cell line (IC50 = 43.08 μM) proved the effectiveness of the developed pharmacophoric model in MMP-9 inhibitor design." (PMID 37569509, 2023). "This study aims to explore the association between MMP-2, MMP-9, and MMP-11 expression with clinicopathologic features among breast cancer patients in Ethiopia." (PMID 37798646, 2023). "Elbaz and colleagues reported that CBD inhibits EGF-induced breast cancer cell proliferation and, interestingly, reduces MMP9 secretion and lung metastasis in vivo." (PMID 37686233, 2023). "Breast cancer studies also acknowledged that CTSK activates pro MMP9 to produce MMP9 that potentiates migration of breast cancer cells to establish distant metastasis." (PMID 37198626, 2023). "By contrast, the downregulation of MMP-2 and MMP-9 expression with the addition of vitamin A was found in various cancer cell lines including breast cancer, lung cancer, glioblastoma, and chondrosarcoma." (PMID 38069361, 2023). "Ruthenium–phloretin complex regulated the PI3K/Akt/mTOR pathway with MMP9 to inhibit tumor invasion and arrest breast cancer progression." (PMID 37701204, 2023). "The use of ADAM8 and MMP-9 antibodies diminished the transmigration of MDA-MB-231 cells, indicating that ADAM8 impacts the levels of transmigration of breast cancer cells by regulating MMP-9." (PMID 36910158, 2023). "In vivo, mouse studies have shown that MMP-13, a “classic collagenase” almost universally upregulated across malignancies, promotes mammary tumor-induced osteolysis by activating MMP-9 and increasing TGF-β signaling at the tumor-bone interface." (PMID 37266453, 2023). "The expression of MMP9 was positive in matrix and cytoplasm of breast cancer cells, and the increase of MMP9 protein levels was related to high tumor grade." (PMID 35874525, 2022). "An in vitro experiment demonstrates that MMP-9 depends on CD44 for cell surface localization in TA3 mouse breast cancer cells, activating TGF-β2 and TGF-β3, which promote cell invasion and angiogenesis." (PMID 36700222, 2022).
breast carcinoma (continued). "Another study also reported decreased tumor growth and angiogenesis by adenoviral gene transfer of MMP-9 in mouse models of human breast cancer (luminal MCF-7 tumors in nude mice and MMTV-PyMT tumors)." (PMID 36741729, 2022). "The aim of this work is therefore to verify the effect of SalB in regulating the in vitro function of MMP-9 in MDA-MB-231 human breast cancer cells." (PMID 36500603, 2022). "Inhibitory monoclonal antibodies targeting a single MMP, mainly MMP-9 or -14, have been developed and demonstrated anti-tumor activity in preclinical models of breast cancer." (PMID 36741729, 2022). "The chemokine CCL2 secreted by MMP11-overexpressing macrophages activates the MAPK pathway, inducing phosphorylation of ERK1/2 and JNK and promotion of HER2+ breast cancer cell migration facilitated by the upregulation of MMP9." (PMID 36591235, 2022). "Molecular markers such as MMP-2 and MMP-9 can be utilized as reference indices to guide the diagnosis and treatment of breast cancer." (PMID 35164236, 2022). "The same phenomenon can be observed for MMP-9 shRNA loaded on GO modified only with PAMAM, where 10 mg of the carrier system was required to deliver 1 mg of the shRNA in breast cancer cells in vitro and in vivo to cause 52% gene silencing." (PMID 35743245, 2022). "MMP-9 is a potential prognostic biomarker for various cancers, including lung, ovarian, pancreatic, and breast cancers." (PMID 35178444, 2022). "Intriguingly, monoclonal populations of shERβ MDA-MB-231 cells demonstrate a strong increase in MMP9 levels following the profile of the MCF-7 breast cancer cells of low metastatic potential." (PMID 35719919, 2022). "The results obtained in the present study revealed that SIRT6 is involved in the modulation of breast cancer cell invasion and migration by regulating MMP-9 expression in MCF-7 and MDA-MB-231 cells." (PMID 35840633, 2022). "TIMELESS was also reported to serve as a tumor suppressor and inhibit breast cancer cell invasion and metastasis by knocking down the expression of MMP9." (PMID 35715407, 2022). "On the other hand, melatonin was shown to downregulate MMP2 and MMP9 expression levels in the gastric mucosa of rats, human gastric cancer cell lines, and human breast cancer cell lines." (PMID 36235740, 2022). "Increased expression of active NF-κB (phospho-p65) and metalloproteinase 9 (MMP9) forms the GEMIN3—NF-κB—MMP9 axis in breast cancer metastases." (PMID 36405016, 2022). "Matriptase mediated downstream protein kinase C (PKC) signaling that led to increased MMP-9 and metastasis of a breast cancer cell line." (PMID 36059515, 2022). "Specifically, breast cancer cells grown on tissue culture plates coated with full-length collagen IV displayed increased secretion of matrix metalloproteinase 9 (MMP9), a pro-metastatic protease." (PMID 35804902, 2022). "This is in line with data from a murine breast cancer model demonstrating that upstream inhibition of COX2 in macrophage leads to downregulation of VEGFA, VEGFC and MMP9 associated with reduced metastasis." (PMID 36551640, 2022). "Many studies documented that STAT-3-mediated breast cancer metastasis happens through the upregulation of MMP9, TWIST, SNAIL and SLUG expression." (PMID 36431925, 2022). "On the other hand, stromal MMP-9 was also shown to play a role in breast cancer, but the effect of stromal MMP-9 was dependent on the genetic background of the mouse stain." (PMID 36741729, 2022). "PKC activity is important for cancer cell migration and is correlated with MMP-9 expression in breast cancer cells." (PMID 35840633, 2022). "Decreased MMP-9 activity was previously correlated with hypoxia and matrix stiffness in breast cancer patients." (PMID 35163668, 2022). "Some studies have demonstrated the pro-tumorigenic or pro-metastatic activity of MMP-9 in vivo, but its effect varied with different mouse models of breast cancer." (PMID 36741729, 2022).
breast carcinoma (continued). "The enzyme-free or the enzyme-mediated Doxo release was assessed at 37 °C, in the absence or in presence of 40 nM of MMP-9, a metalloproteinase usually over-expressed in breast cancer cells." (PMID 35893800, 2022). "The fact that crocin downregulated the VEGF gene recalls previous reports that crocin, metformin, and the combination treatment resulted in a dramatic decrease in the VEGF and MMP9 protein content in a mice induced breast cancer." (PMID 36139719, 2022). "In the present study, we measured the expression of MMP-2 and MMP-9 in breast cancer patients and determined their correlations with SPHK1 and CERK in local as well as TCGA cohort." (PMID 36309544, 2022). "Using the breast cancer model, blocking MMP9 with an active form-specific monoclonal antibody was found to abolish cancer cell colonization in the premetastatic lung niche." (PMID 35406619, 2022). "Recently, many studies evaluated the potential of MMP-9 as a biomarker for the prognosis of various cancers, including cervical, ovarian, pancreatic, and breast cancers." (PMID 35178444, 2022). "To establish the role of sphingolipids in breast cancer metastasis, we analyzed the associations of MMP-2 and MMP-9 with SPHK1 and CERK expression." (PMID 36309544, 2022). "MMPs exist in six different families, in which gelatinases such as MMP-2 and MMP-9 are the essential enzymes in the invasion and dissemination of breast cancer cells." (PMID 35164236, 2022). "For example, high serum levels of TIMP1 are promising indicators of poor overall survival of breast cancer patients, whereas high serum levels of MMP-9 have been demonstrated to strongly predict response to treatment and metastasis." (PMID 35818030, 2022). "Another study showed that MMP-9 expression in breast cancer was a predictor of shorter survival of patients and that MMP-9 was associated with higher tumor grade and a confirmed positive association between MMP-9 and ECM remodeling." (PMID 35742125, 2022). "An early study using xenograft models of luminal A MCF-7 breast cancer cells showed that secreted MMP-9 promotes tumor growth and angiogenesis." (PMID 36741729, 2022). "Studies have shown that the use of DCH reduces MMP2 and MMP9 activity in breast cancer and oral squamous cell carcinoma." (PMID 36408277, 2022). "LARP6 is overexpressed in breast cancer and promotes angiogenesis by upregulating the expression of MMP-9 and VEGF." (PMID 36052258, 2022). "KLF8 promotes human breast cancer cell invasion and metastasis by transcriptional activation of MMP9." (PMID 35205261, 2022). "Ayse identified significant changes in intratumoral MMP9 expression during anti-PD1 therapy in breast cancer patients using single-cell sequencing technology." (PMID 36189226, 2022). "MMP-9 is a vital component of the metastatic niche during tumorigenesis and can promote the breast cancer cells to colonize the lungs." (PMID 36003508, 2022). "Following the expression profile of TIMP‐1, the activity of MMP‐1 was significantly lower in spheroids with hASCs and breast cancer cells than in spheroids from other models, while the activity of MMP‐9 was similar among spheroids." (PMID 35600659, 2022). "ADAM8 and MMP9 levels are correlated in GBM tissue samples as well breast cancer-derived brain metastasis." (PMID 35371977, 2022). "Flow was also a poor inducer of the metalloprotease genes MMP2 and MMP9 in the breast cancer cell lines evaluated, suggesting that WSS of low magnitude likely plays little role in stimulating breast cancer invasion into extracellular matrices." (PMID 35520391, 2022). "It was also found to reduce the concentration of MMP9 in rat retina, human ovarian cells, and breast cancer cells." (PMID 36235740, 2022). "Previously, we demonstrated that ADAM8-dependent MMP9 expression is mediated via the MAPK pathway and resulted in a strong correlation of ADAM8 and MMP9 in breast cancer-derived brain metastasis." (PMID 35371977, 2022).
breast carcinoma (continued). "A recent systematic review and meta-analysis also demonstrated that tumoral MMP-9 overexpression correlates with lymph node metastasis and predicts shorter OS in breast cancer patients." (PMID 36741729, 2022). "Yu and Stamenkovic showed that MMP9 colocalized with the hyaluronan (HA) receptor CD44 on the mouse mammary carcinoma and melanoma cell surface." (PMID 35406619, 2022). "We found that both Mmp9 and Mmp10 genes are upregulated in primary tumors of human breast cancer patients compared to normal solid tissue." (PMID 36612044, 2022). "We previously reported that tGLI1 modulates the invasion of glioblastomas and breast cancer through the upregulation of heparanase and MMP9 expression, respectively." (PMID 36077791, 2022). "In a study conducted in 2014, the serum levels of MMP-9 in 77 patients with breast cancer were quantified through ELISA." (PMID 35818030, 2022). "MMP-9 plays an important role in the onset, progression, and metastasis of gastric, lung, colon, and breast cancers." (PMID 35178444, 2022). "Based on the previous study, the mechanism research, which about MMP9 promotes breast cancer progression by regulating fatty acid metabolism, possibly serving as a therapeutic strategy in breast cancer." (PMID 35852149, 2022). "MMP-9 is significantly induced in breast cancer tissues and here also shows the increasing levels of expression in MDA-MB-231 cells when treated with WFs." (PMID 35538133, 2022). "Several papers demonstrated that, in experimental tumor models among which breast cancer is included, a correlation between NF-kB and MMP-9 exists." (PMID 36290354, 2022). "Orosomucoid 1 (ORM1) upregulates the expression of matrix metalloproteinases (MMP-2 and MMP-9) consequently promoting epirubicin resistance in breast cancer." (PMID 36699376, 2022). "A study on breast cancer showed that MMP9 was secreted predominantly by fibroblasts, and its expression in tumor fibroblasts is regulated by multiple cytokines and complex cellular signaling pathways." (PMID 36591235, 2022). "Several studies have reported that TPA activates the synthesis and secretion of MMP-9 in breast cancer cells." (PMID 35840633, 2022). "We aimed to evaluate the contribution and association of single-nucleotide polymorphisms (SNPs) in MMP genes (MMP1, MMP2, MMP3, MMP7, MMP8, MMP9) with clinicopathological breast-cancer features." (PMID 36009438, 2022). "Since MMP‐1 and MMP‐9 have been reported to play crucial roles in breast cancer, the activities of MMP‐1 and MMP‐9 in spheroid‐conditioned media were also analyzed." (PMID 35600659, 2022). "TPA dramatically induces the invasion of human breast cancer cells by upregulating MMP-9 expression via transcription factors and MAPK pathways." (PMID 35840633, 2022). "A monoclonal antibody against murine MMP-9 (AB0046) decreased primary growth in an orthotopic model of HER2-driven breast cancer (HC11-NeuT) in immunocompetent mice." (PMID 36741729, 2022). "By promoting the expression of integrin 1 by acting on its promoter, SIPA1 further activates the phosphorylation of FAK, and thus regulates invasiveness and morphology of breast cancer cells through the MMP9 signaling and F-actin, respectively." (PMID 35431649, 2022). "Others have shown that breast-cancer-cell-derived miR-429 reduces osteoclast differentiation in vitro via MMP-9 and V-crk sarcoma virus CT10 oncogene homolog-like (CrkL)." (PMID 35158995, 2022). "Taken together, these results illustrate that tumor cell-produced or stromal cell-derived MMP-9 can exert pro-tumorigenic or pro-metastatic roles in breast cancer under certain circumstances." (PMID 36741729, 2022). "Others have shown that overexpression of miR-20a-5p in MDA-MB-231 breast cancer cells increases the expression of MMP-2 and MMP-9, which is associated with increased migration and invasion in vitro." (PMID 35158995, 2022).
breast carcinoma (continued). "In accordance, MDA-MB-231 were among those cell lines that showed a strong correlation between ADAM8 and MMP9 expression in our previous study on breast cancer-derived brain metastases." (PMID 35371977, 2022). "In contrast, in the MMTV-PyMT luminal B breast cancer model, blocking active MMP-9 with a monoclonal antibody suppressed lung metastasis without affecting primary tumor growth." (PMID 36741729, 2022). "MMP-2 and MMP-9 are highly expressed in malignant tumors and positively correlate with an aggressive malignant phenotype and poor outcome in breast cancer patients." (PMID 33633298, 2021). "MMP-9 and FAK are associated with MDA-MB-231 breast cancer cell growth factor mediated motility and invasion." (PMID 33968759, 2021). "Breast cancer cell lines used in the study are characterized by the high expression of both proteins, and after downregulation of MMP-9 level, the expression of CK19 also decreased." (PMID 34884588, 2021). "As a result, decreased CPEB1 expression lengthens the poly(A) tail resulting in increased Matrix Metallopeptidase 9 (MMP9) mRNA translation in breast cancer." (PMID 33923168, 2021). "Further validation of gene expression by using GEPIA revealed that the mRNA expression of MMP9 was significantly higher in breast cancer tissues than in normal tissues, whereas the mRNA expression of PTGS2 showed the opposite." (PMID 34335799, 2021). "Western blot proved that the metastasis associated proteins MMP9 and FAK expression were inhibited in the miR-18a-3p inhibitor group, and inhibited expression of miR-18a-3p can enhance the function of HHT on breast cancer cells." (PMID 33867824, 2021). "S1P induces the expression of MMP2 in endothelial cells, MMP7 in hepatocellular carcinoma cells, and MMP9 in breast cancer cells." (PMID 34262394, 2021). "MMP9 synthesized in breast cancer cells is important for invasion and lung metastasis in a mouse orthotopic model of basal-like breast cancer." (PMID 34643237, 2021). "We also observed a notable inhibition of EMT markers–vimentin and matrix metalloproteinase 9 (MMP-9) that play a crucial role in breast cancer metastasis with ATQ treatment." (PMID 34071408, 2021). "In other experimental conditions, PGJ2 reduced the expression of MMP-9 and breast cancer MCF-7 cell invasiveness, IL-6 production and neutrophil recruitment in gout arthritis, and mast cell infiltration in atopic dermatitis." (PMID 34764817, 2021). "Luteolin (8-C-β-d-glucopyranoside), a glycosyl dietary flavonoid, reduces tumor invasion, into 12-O-tetradecanoylphorbol-13-acetate (TPA)-treated MCF-7 breast cancer cells, blocking expression of MMP-9 metalloproteinase and interleukin-8 (IL-8)." (PMID 34208196, 2021). "In summary, this study reports that BSP protein expression in MDA-MB-231 breast cancer cells is enhanced upon incubation with collagen 1, basement membrane extract, and short-term proteolytic treatment using dispase or MMP-9." (PMID 34073955, 2021). "MHP-1 also inhibited the protein levels of slug, suppressed EMT breast cancer, and decreased MMP-9 secretion." (PMID 34200897, 2021). "To explore the mechanisms underlying the regulation of migration and invasion in breast cancer cells following sauchinone treatment, we first screened representative MMPs (MMP2, MMP3, MMP9, and MMP13) via immunoblotting analysis." (PMID 34643237, 2021). "As for the subtype analysis, overexpression of MMP9 revealed itself as a prominent feature of Basel and Her2 breast cancers, which was almost consistent with our results." (PMID 35069702, 2021). "TCGA dataset confirmed that breast cancer is characterized by the overexpression of MMP-9 and CK19 mRNA." (PMID 34884588, 2021). "Then, we checked if the overexpression of MMP-9 has an impact on breast cancer patients’ overall survival." (PMID 34884588, 2021). "TIMELESS can inhibit the breast cancer cell invasion and metastasis by downregulating MMP9 expression." (PMID 34490127, 2021).